NEAT1 (nuclear paraspeckle assembly transcript 1)
Diseases named in the same sentence as NEAT1 in open-access papers (continued):
Sharing a sentence is not in itself a finding about the gene and the disease.
influenza infection (3 papers, 2021 to 2025). "Given that a dose-dependent upregulation of NEAT1 occurs during IAV infection, the detection of differentially expressed NEAT1 in the serum of influenza patients may represent a potential diagnostic approach for monitoring disease progression." (PMID 41208976, 2025). "NEAT1 is up-regulated in HIV-1, dengue, HSV-1, Hantavirus, Hepatitis D and influenza infections." (PMID 36279270, 2022). "NEAT1, EGOT, NRON, and lncRNA-CMPK2 have been reported as lncRNAs regulated by the hepatitis C and B viruses (HCV and HBV) while NEAT1 is upregulated in HIV, encephalitis, and influenza infections." (PMID 34830125, 2021).
injury (3 papers, 2020 to 2025). Damage inflicted on the body as the direct or indirect result of an external force, with or without disruption of structural continuity. "Functional heterogeneity is evident in NEAT1: Global suppression dysregulates synaptic plasticity, whereas pharmacological induction by bexarotene elevates NEAT1 to attenuate Pidd1-caspase-2 signaling in traumatic brain injury." (PMID 40777664, 2025).
intrauterine growth restriction (3 papers, 2017 to 2024). "Neat1 localises villous trophoblast nuclei, and Neat1 mRNA expression was up-regulated in placentas of mice undergoing intrauterine growth restriction (IUGR), indicating Neat1 might play a role in placental dysfunction in idiopathic IUGR foetuses." (PMID 29137430, 2017). "LncRNA nuclear-enriched abundant transcript-1 (NEAT1) expression in the placenta of fetuses with intrauterine growth restriction was higher than that of fetuses without intrauterine growth restriction at term, suggesting that NEAT1 may have a major role in pregnancy." (PMID 38709402, 2024).
kidney injury (3 papers, 2020 to 2021). Trauma to the kidney. "The interaction between NEAT1, PVT1, miR-429, miR-139-5p, and miR-23b-3p may regulate CaOx-induced kidney injury via CCL7 and ROBO2." (PMID 34938320, 2021).
liver disease (3 papers, 2019 to 2023). "Another therapeutic pathway recently discovered in the carbon tetrachloride mouse model that offers promise in the progression of liver disease is the lncRNA nuclear paraspeckle assembly transcript 1 (NEAT1) discovered in primary mouse hepatic stellate cells (HSCs)." (PMID 31731549, 2019). "Studies have shown that the increase of NEAT1 has been observed in various cancers, liver diseases, non-alcoholic fatty liver disease (NAFLD), and liver fibrosis." (PMID 37169818, 2023).
liver failure (3 papers, 2020 to 2025). A liver disease characterized by the liver losing or has lost all of its function. "Low expression of NEAT1 was associated with more than a 5-fold higher probability of anemia (OR = 5.26; p = 0.020) and nearly a 6-fold higher chance of liver failure (OR = 5.70; p = 0.016) after the completion of RT." (PMID 40150019, 2025). "Our study demonstrates that both low MALAT1 and NEAT1 expression levels are significantly associated with a higher probability of post-RT adverse effects, including anemia, liver failure, and nutritional deficiencies." (PMID 40150019, 2025). "Similarly, patients with low NEAT1 expression had a significantly higher risk of anemia, liver failure, and mild or severe malnutrition (OR = 5.26; p = 0.020, OR = 5.70; p = 0.016, OR = 13.09; p = 0.002, respectively)." (PMID 40150019, 2025). "LC patients with poor performance status (ECOG) (OR = 4.62; p = 0.047), as well as lower MALAT1 expression (OR = 1.49; p = 0.015) and NEAT1 expression (OR = 9.09; p = 0.005), had a significantly greater likelihood of liver failure." (PMID 40150019, 2025). "Our results are consistent with these findings, as we observed a higher frequency of anemia and liver failure in patients with a lower expression not only of MALAT1 but also of NEAT1." (PMID 40150019, 2025). "To further investigate the mechanism regulating the liver failure, we detected the expression levels of lncRNA NEAT1 in patient serum samples with ALF and D-GalN/LPS-induced ALF murine liver tissues." (PMID 33901015, 2021). "Long noncoding RNA NEAT1 (nuclear-enriched abundant transcript 1) inhibited hepatocyte proliferation in fulminant hepatic failure via strengthened recruitment of EZH2 to the LATS2 (large tumor-suppressor kinase 2) promoter region." (PMID 33028420, 2020). "Additionally, NEAT1 was effective in discriminating between patients with liver failure, showing 78.95% sensitivity and 60% specificity (AUC = 0.71; cut-off > 0.20; p < 0.006)." (PMID 40150019, 2025). "Additionally, patients with liver failure had a significantly lower expression of both MALAT1 (median: 0.32 vs. 0.47; p = 0.013) and NEAT1 (median: 0.32 vs. 0.44; p = 0.026)." (PMID 40150019, 2025).
lupus nephritis (3 papers, 2020 to 2025). Glomerulonephritis in the context of systemic lupus erythematosus. "It is reported that NEAT1 may also promote renal inflammation in lupus nephritis by upregulating the expression of TRAF6 and activating the NF-κB signaling in lupus nephritis." (PMID 34054586, 2021). "Nuclear enriched abundant transcript 1 (NEAT1), a novel lncRNA, accelerated renal mesangial cell injury by directly targeting miR-146b, promoting the expression of TRAF6, and activating the NF-κB signaling in lupus nephritis." (PMID 33294443, 2020).
metastatic tumor (3 papers, 2016 to 2020). "Noteworthy in this study is that we demonstrated that mtr-miR5754 and gma-miR4995 directly target the transcripts of two lncRNAs, MALAT1, and NEAT1, which are both associated with almost all type of tumors and in particular with the metastatic tumor process." (PMID 33193626, 2020).
pancreatic ductal adenocarcinoma (3 papers, 2018 to 2022). An infiltrating adenocarcinoma that arises from the epithelial cells of the pancreas. "In the case of a pancreatic ductal adenocarcinoma model induced by conditional KRasG12D overexpression, acinar-to-ductal metaplasia formation is enhanced in Neat1 KO mice, suggesting that Neat1 functions as a tumour suppressor." (PMID 30355755, 2018).
prostate tumor (3 papers, 2014 to 2024). "An increase in transcript levels of the long noncoding RNA the NEAT1 causes a resistance to docetaxel in prostate tumors." (PMID 39512820, 2024). "The overexpression of lncRNA NEAT1 induces docetaxel resistance in prostate tumor." (PMID 35773731, 2022). "We hypothesized that targeting NEAT1 using mechanisms that can constrain ERα might represent a novel therapeutic strategy in prostate tumours that are resistant to anti-androgen therapy." (PMID 25415230, 2014). "Because it acts as an upstream mediator, the long noncoding RNA NEAT1 brings down the levels of miRNA-204-5p and miRNA-34a-5p, which in turn raises the expression of ACSL4, which ultimately results in prostate tumor cells being resistant to docetaxel." (PMID 39512820, 2024). "As an upstream mediator, lncRNA NEAT1 down-regulates expression level of both miRNA-34a-5p and miRNA-204-5p to elevate ACSL4 expressions, leading to docetaxel resistance of prostate tumor cells." (PMID 35773731, 2022).
proteinopathies (3 papers, 2022 to 2023). "Recent studies have started to uncover complex relationships between TDP-43 and the lncRNA NEAT1 in TDP-43 proteinopathies, and we now turn to this theme." (PMID 36385948, 2022). "Furthermore, the overexpression of lncRNA NEAT1 ameliorates the toxicity of TDP-43 in Drosophila and in TDP-43 protein disease yeast models, which can lead to the conclusion that NEAT1 upregulation may be protective against TDP-43 proteinopathies affecting the brain." (PMID 36499048, 2022).
rectal cancer (3 papers, 2024 to 2026). A primary or metastatic malignant neoplasm that affects the rectum. "Six of the seven included papers had an association between lncRNA NEAT1 expression and rectal cancer differentiation, of which 276 patients were highly/moderately differentiated and 113 patients were poorly differentiated." (PMID 39139172, 2024). "This investigation is crucial for enhancing our understanding of NEAT1’s role in rectal cancer, which could have significant diagnostic and therapeutic implications." (PMID 39139172, 2024). "PubMed, EMBASE, Cochrane library database and case-control studies on the correlation between abnormal expression of lncRNA NEAT1 and prognosis of rectal cancer patients published by the American clinical trials registry before May 1, 2023 were searched." (PMID 39139172, 2024). "This study underscores the significance of NEAT1 in rectal cancer prognosis and highlights the potential for developing NEAT1-targeted therapeutic strategies, thereby contributing to more effective patient management and treatment outcomes in rectal cancer care." (PMID 39139172, 2024).
skin cancer (3 papers, 2017 to 2020).
ulcerative colitis (3 papers, 2022 to 2025). An inflammatory bowel disease involving the mucosal surface of the large intestine and rectum. "In ulcerative colitis, NEAT1 upregulation contributes to inflammation and epithelial injury through multiple regulatory pathways." (PMID 41465348, 2025). "Expressions NEAT1 and miR-410-3p were compared in intestinal epithelial cells isolated from ulcerative colitis tissues and healthy controls." (PMID 35735114, 2022). "In summary, these results unveiled new roles and molecular mechanisms for the NEAT1-mediated IECs dysfunction during the ulcerative colitis." (PMID 35735114, 2022). "This study aimed to investigate the roles and molecular mechanisms of lncRNA NEAT1 and miR-410-3p in the pathological processes of ulcerative colitis." (PMID 35735114, 2022).
acute respiratory distress syndrome (2 papers, 2021 to 2022). Progressive and life-threatening pulmonary distress in the absence of an underlying pulmonary condition, usually following major trauma or surgery. "For example, NEAT1 was found to exacerbate acute lung injury (ALI) and acute respiratory distress syndrome (ARDS) by inducing alveolar epithelial cell injury and inflammation via HMGB1/RAGE axis." (PMID 34151707, 2021). "In LPS-induced ALI mice models, lncRNA nuclear paraspeckle assembly transcript 1 (NEAT1) may induce alveolar epithelial cell injury and inflammation through HMGB1, thereby aggravating the progression of ALI and acute respiratory distress syndrome (ARDS)." (PMID 35720285, 2022).
Adenovirus infection (2 papers, 2020 to 2022). "Polyomavirus and adenovirus infections are also associated with glioma development, and adenovirus infection promotes GBM stem cell formation through the TLR9/NEAT1/STAT3 pathway." (PMID 36497459, 2022).
AIDS (2 papers, 2015 to 2021). A syndrome resulting from the acquired deficiency of cellular immunity caused by the human immunodeficiency virus (HIV). "Many host proteins and RNAs have been characterized for their roles in HIV/AIDS pathogenesis, but there is only one lncRNA, NEAT1, which is shown to affect the HIV-1 life cycle." (PMID 25728138, 2015).
alcoholic steatohepatitis (2 papers, 2020 to 2024). "However, the role of NEAT1 in regulation of alcoholic steatohepatitis (ASH) remains largely unknown." (PMID 33228663, 2020).
Atrophy (2 papers, 2019 to 2020). Any weakening or degeneration, especially through lack of use. "We found that 2310065F04Rik (linc-Myh) resulted down-regulated in both atrophy models while Dancr, Gas5, H19, Igf2os, Airn, MiR22hg, Neat1 and Snhg1 were up-regulated in the late phases of atrophy." (PMID 30649422, 2019).
auto-inflammatory syndromes (2 papers, 2019 to 2021). "Therefore, Neat1 may represent a therapeutic target for inflammasome-associated diseases such as gout and autoinflammatory syndromes." (PMID 30940803, 2019).
bacterial meningitis (2 papers, 2022 to 2024). Inflammation of the membranes surrounding the brain and spinal cord due to a bacterial infection. "Inhibition of lncRNA nuclear paraspeckle assembly transcript 1 (NEAT1) expression can increase miR-135a expression and reduce the blood-brain barrier (BBB) permeability in vitro bacterial meningitis-induced BBB damage models." (PMID 38347610, 2024). "On the other hand, overexpression of NEAT1 increased BBB permeability in both in vitro and in vivo bacterial meningitis models." (PMID 35346266, 2022). "Downregulation of NEAT1 effectively maintained BBB integrity and decreased BBB permeability in bacterial meningitis experimental models through upregulating miR-135a and downregulating HIF1α to increase the expression of ZO-1, occludin, and claudin-5." (PMID 35346266, 2022).
bone cancer (2 papers, 2021 to 2024). A primary or metastatic malignant neoplasm affecting the bone or articular cartilage. "The lncRNA NEAT1 acts as a bridge between CYCLINL1 and CDK19 to promote Pol II ser2 phosphorylation, which might represent a new target for the treatment and diagnosis of bone cancer metastasis." (PMID 34777473, 2021).
brain injury (2 papers, 2020). Acute and chronic (see also brain INJURIES, CHRONIC) injuries to the brain, including the cerebral hemispheres, CEREBELLUM, and brain STEM. "The anti-inflammatory efficacy of NEAT1 also has been demonstrated in mice with traumatic brain injury." (PMID 32089649, 2020). "In contrast, NEAT1 affords antiapoptotic and anti-inflammatory functions in traumatic brain injury." (PMID 32089649, 2020).
cardiac hypertrophy (2 papers, 2019 to 2023). "Additionally, several lncRNAs also regulate cardiac hypertrophy, such as lncRNA AK006774 and NEAT1." (PMID 37197359, 2023).
cervical tumor (2 papers, 2020 to 2021). "For example, although EHF and NEAT1 are known cytoplasmic targets of miR-365 regulation in oral caners, the potential for miR-365 to modulate other targets has been verified in additional cancers, such as breast skin, lung, liver, and cervical tumors." (PMID 32727045, 2020).
chronic liver failure (2 papers, 2020 to 2021). Liver failure that develops slowly and gradually for some time, possibly for years, often as the result of cirrhosis, or malnutrition. "In acute-on chronic liver failure, overexpression of NEAT1 decreased the ubiquitination level of TRAF6 and inflammatory response." (PMID 34837887, 2021).
chronic obstructive pulmonary disease (2 papers, 2022). A chronic and progressive lung disorder characterized by the loss of elasticity of the bronchial tree and the air sacs, destruction of the air sacs wall, thickening of the bronchial wall, and mucous accumulation in the bronchial tree. "Moreover, NEAT1 also increases PINK1 and parkin expression, thereby enhancing lung mitophagy in chronic obstructive pulmonary disease." (PMID 36430876, 2022).
Cirrhosis (2 papers, 2022 to 2023). A chronic disorder of the liver in which liver tissue becomes scarred and is partially replaced by regenerative nodules and fibrotic tissue resulting in loss of liver function. "Genome‐wide association study (GWAS) summary statistics were extracted from seven studies (>1.7 million participants) for variants near ACVR2A, ALB, CIDEB, FOXO1, GPAM, NEAT1 and TNRC6B for: aminotransferases, liver fat, HbA1c, diagnosis of NAFLD, ARLD and cirrhosis." (PMID 35474605, 2022).
colitis (2 papers, 2023 to 2025). Inflammation of the colon. "Elevated NEAT1 expression in colitis mouse models has been shown to exacerbate inflammation by disrupting epithelial barrier integrity and modulating macrophage polarization through exosome-mediated signaling." (PMID 41465348, 2025).
colon adenocarcinoma (2 papers, 2019 to 2025). "Induction of NEAT1 expression levels due to rs3825071 polymorphisms led to a poorer survival of younger patients with colon adenocarcinoma." (PMID 41323778, 2025). "Moreover, further analysis of data from patients with colon adenocarcinoma in TCGA dataset revealed that cases of the younger age group (< 65 years old) with tumors expressing higher levels of NEAT1 exhibited a worse survival rate than those with tumors expressing lower levels of NEAT1." (PMID 41323778, 2025).
encephalitis (2 papers, 2021 to 2025). An acute inflammatory process affecting the brain parenchyma. "Notable lncRNA nodes, such as Zfas1, Gm20559, Neat1, C0300018K13Rik, and A230001M10Rik, were identified as central hubs, connecting to multiple target mRNAs, highlighting these transcripts as key lncRNAs in PRV-induced encephalitis." (PMID 41214723, 2025).
gynecologic cancers (2 papers, 2021 to 2023). "Among them, the clinical significance of NEAT1 is evaluated in several studies and the findings have suggested this lncRNA with applications in diagnosis and treatment of patients with gynecological cancers." (PMID 37310654, 2023). "It has been reported that NEAT1 by targeting various axes plays a role in the pathogenesis of gynecologic cancers." (PMID 37310654, 2023). "In this review, we summarized several NEAT1/miRNA/mRNA pathways that are critical in the pathogenesis of gynecologic cancers." (PMID 37310654, 2023). "Taken together, along with an increasing number of lncRNAs, NEAT1 is also suggested with potentials in prediction of prognosis, helping diagnosis and a therapeutic target for patients with gynecologic cancers." (PMID 37310654, 2023). "In this narrative review, we summarized various NEAT1-related signaling pathways that are critical in gynecologic cancers." (PMID 37310654, 2023). "Taken together, NEAT1 can be used as a potential biomarker for the treatment of gynecologic cancers." (PMID 37310654, 2023). "We further provide various perspectives on the association of some lncRNAs, i.e., HOTAIR, NEAT1, H19, MALAT1, and MEG3, in terms of invasion, proliferation, metastasis, apoptosis, and drug resistance of breast and gynecological cancers based on recent discoveries." (PMID 34885213, 2021). "Therefore, targeting NEAT1-miRNAs suggests novel therapeutic targets in gynecologic cancers." (PMID 37310654, 2023). "Nuclear paraspeckle assembly transcript 1 (NEAT1) is a lncRNA that mediates cell proliferation, migration, and EMT in gynecologic cancers by targeting several miRNAs/mRNA axes." (PMID 37310654, 2023). "In this article, we present a summary of the progress on ascertaining the biological functions of five lncRNAs (HOTAIR, NEAT1, H19, MALAT1, and MEG3) in female-oriented cancers, including breast and gynecological cancers, with the perspective of carcinogenesis, cancer proliferation, and metastasis." (PMID 34885213, 2021). "Therefore, in this article, we highlight the role of various lncRNAs and specifically five lncRNAs—HOTAIR, NEAT1, H19, MALAT1, and MEG3—in cancers unique to women, including breast and gynecological cancers." (PMID 34885213, 2021).
Hepatic steatosis (2 papers, 2020). Steatosis is a term used to denote lipid accumulation within hepatocytes. "Thus, NEAT1 participates in the activation of ERα to modulate AQP7-associated hepatic steatosis." (PMID 32759784, 2020). "The 3′ terminal region of nuclear enriched abundant transcript 1 (NEAT1) has been shown to interact with ERα to enhance expression of Aquaporin 7 (AQP7) and subsequently inhibit liver steatosis." (PMID 32759784, 2020).
Herpes simplex infections (2 papers, 2019 to 2021). "First advances towards a therapeutic application of NEAT1 have been made in the context of Herpes simplex infection where virus-induced skin lesions have successfully been treated with gels containing NEAT1 siRNA." (PMID 30717168, 2019). "Initial advances pertaining to therapeutic interventions by NEAT1 modulation show that in the case of herpes simplex infection, thermosensitive gels coated with siRNA against NEAT1 were able to reduce virus induced skin lesions." (PMID 30717168, 2019).